IDO1 (indoleamine 2,3-dioxygenase 1)
Diseases named in the same sentence as IDO1 in open-access papers (continued):
Sharing a sentence is not in itself a finding about the gene and the disease.
lung carcinoma (continued). "Another trial focused on lung cancer cells confirms that IDO1 activity is crucial for metastasis occurrence, and its inhibition improves patient outcomes." (PMID 34071442, 2021). "Surprisingly, immune checkpoint molecules PD‐L1, PD‐L2, and IDO1 were found to be highly expressed in brain metastases from lung cancer." (PMID 32017467, 2020). "Inhibition of IDO1 through pharmacological inhibition reduced the viability of cisplatin-resistant lung cancer cells via induction of increased generation of ROS." (PMID 32266129, 2020). "In order to verify the precise mechanism of GBP1 and IDO1 interaction and its role in lung cancer cells, we simulated the interaction between GBP1 and IDO1 using molecular docking." (PMID 33552086, 2020). "The interaction of GBP1 and IDO1 induced the extracellular secretion of IDO1 promote lung cancer cell progression." (PMID 33552086, 2020). "Especially, immune checkpoint molecules, PD‐L1, PD‐L2, and IDO1 were expressed at higher levels in brain metastases from lung cancer than those from the other two cancer types." (PMID 32017467, 2020). "HIV: bacterial translocation, inflammation, mortalityCancer: Overexpressed in tumoral cells (e.g., endometrial cancer, lung cancer) IDO1 inhibitors under evaluation in both conditions." (PMID 31316514, 2019). "IDO1 is an immune checkpoint gene involved in lung cancer progression and metastasis and thus a promising target for lung cancer immunotherapy." (PMID 29484121, 2018). "Taken together, these data indicates that IDO1 has a close relationship with lymph node-metastasis and acts as metastatic modulator in lung cancer." (PMID 28903363, 2017). "We also found that advanced stages (stage III) had a higher IDO1 expression than early stages in lung cancer (stage I and II)." (PMID 28903363, 2017). "In present study, our discovery revealed that high IDO1 expression was significantly correlated with lymph node-metastasis, as the lung cancer with lymph node-metastasis had a much higher IDO1 expression than those without lymph node-metastasis." (PMID 28903363, 2017). "It has been recently reported that a high intratumor amount of IDO1 favors the growth of lung cancers." (PMID 25955018, 2015). "Most importantly, high IDO1, STAT3 and CYP1B1 expression was associated with reduced relapse-free survival in lung carcinoma patients." (PMID 24657910, 2014). "GBP1 has been shown to promote proliferation, migration, and metastasis in lung cancer by binding to indoleamine 2,3-dioxygenase 1 (IDO1) and to enhance resistance to epidermal growth factor receptor (EGFR) inhibitors by interacting with phosphoglycerate kinase 1 (PGK1)." (PMID 40975978, 2025). "IDO1 inhibitors have shown greater efficacy in cisplatin‐resistant lung cancer patients." (PMID 41332472, 2025). "Moreover, IDO1 induces NK cell dysfunction via downregulation of the activating receptor NKG2D on NK cells by inhibiting NKG2D ligand (NGD2DL) expression on lung cancer cells via the IDO1-Kyn-AhR signaling pathway." (PMID 40361394, 2025). "Additionally, TNF-α, IL-6, and IL-1β induce elevated Ido1 expression in the context of immunosuppression in lung cancer progression." (PMID 39759510, 2024). "Furthermore, blocking the T cell exhaustion induced by IDO1 can enhance the performance of PD-1 inhibitors in lung cancer treatment." (PMID 39726592, 2024). "Collectively, the findings suggested that QFM may increase the influences of PD-1 inhibitors at least partially by blocking the STAT1/IDO1-mediated tryptophan-kynurenine pathway in lung cancer." (PMID 38882349, 2024). "We chose 7 lung cancer cell lines based on the variable levels of expression of IDO1 and TDO2." (PMID 37985999, 2023).
lung carcinoma (continued). "This IDO1 induction is concomitant with an increase in PD-L1 and PD-L2 and together, may provide the lung cancer cells a survival advantage by Kyn-dependent or PD-L1/2-PD-1-mediated inhibition of T-cell activity." (PMID 37985999, 2023). "Similarly, the higher expression of IDO1 in 13 primary lung cancer and their matched-paired samples we discovered previously, confirming the results of our study." (PMID 38149244, 2023). "The human lung cancer cells require 100 times more of the mouse derived IL-1β to generate an IDO1/PD-L1 response that is seen with the human-derived IL-1β, indicating that further in vivo characterization needs to be performed in syngeneic or humanized mouse models." (PMID 37985999, 2023). "Recently, it was reported that myricetin inhibits interferon-γ-induced programmed death ligand-1 (PD-L1) and indoleamine 2,3-dioxygenase 1 (IDO1) expression in lung cancer cells via the regulation of the Janus kinase/signal transducer and activator of the JAK/STAT-IRF1 transcription pathway." (PMID 37764304, 2023). "Relative expression of IDO1 mRNA levels were shown to be higher in lung tumor samples relative to lung cancer cell lines, indicating that factors within the tumor microenvironment could induce IDO1 expression." (PMID 37985999, 2023). "Level of IDO1 expression in combination with the clinical stage of lung adenocarcinoma could be used to evaluate the feasibility of radical surgery of the lung cancer." (PMID 35187162, 2022). "IDO1 activity also predicts the efficacy of chemotherapy or immunotherapy in lung cancer patients." (PMID 36032151, 2022). "In addition, the upregulation of IDO1 by NNK provides a new example of an environment-gene interaction in lung cancer." (PMID 36068203, 2022). "In lung cancer patients, previous studies reported that high expression of IDO1 was associated with poor prognosis and survival in non-small-cell lung cancer, and IDO1 activity was linked to primary resistance to immunotherapy in non-small-cell lung cancer." (PMID 35187162, 2022). "Moreover, knockdown of IDO1 suppressed the metastatic development of cancer cells as demonstrated for KRAS-induced lung carcinoma." (PMID 34769098, 2021). "Until now, lung cancer is the most-studied tumor type in clinical trials of IDO1 inhibitors." (PMID 33557876, 2021). "Indoleamine 2,3-dioxygenase 1 (IDO1) inhibition within the range of IDO1-expressing myeloid-derived suppressor cells in a mouse model of lung cancer decreased the size of the population of these cells, increased the immunosuppressive effect and sensitized the tumor to radiation." (PMID 32488850, 2020). "Interestingly, PD‐L1/CD274, PD‐L2/PDCDLG2, and IDO1, which belong to the checkpoint pathways, were highly expressed in the brain metastases of lung cancer." (PMID 32017467, 2020). "In addition, astragaloside IV can block the interaction between GBP1 and IDO1 and enhance the inhibitory effect of PD-1 inhibitors of lung cancer cell in vivo and in vitro." (PMID 33552086, 2020). "These experiments indicated that IDO1 and GBP1 contributed to the malignant progression of lung cancer, which may due to the interaction between IDO1 and GBP1." (PMID 33552086, 2020). "Astragaloside IV can block the combination of IDO1 and GBP1 to prevent the exhaustion of T cells caused by the extracellular secretion of IDO1, and further enhance the inhibitory effect of PD-1 inhibitors in lung cancer." (PMID 33552086, 2020). "Additionally, IDO-1 has been shown to induce immunosuppressive effects and favor tumor progression in animal models of lung cancer." (PMID 28903363, 2017). "Interestingly, we discovered that over-expression of IDO1 significantly promoted metastasis and invasion of lung cancer cells." (PMID 28903363, 2017).
lung carcinoma (continued). "Currently, we found that IDO1 expression increased in lung cancer contrast with the corresponding non-tumor tissues, and the up-regulation of IDO1 is associated with TNM stage and lymph node-metastasis." (PMID 28903363, 2017). "The over-expression of IDO1 significantly encouraged the metastasis and invasion of lung cancer cells, and IDO1 could promote metastasis formation in vivo." (PMID 28903363, 2017). "Taken together, our results suggest that IDO1 is a positive regulator for lung cancer metastasis." (PMID 28903363, 2017). "Therefore, we established NCI-H292 and HCC827 cell lines that stably express IDO1 by lentivirus infection, as NCI-H292 and HCC827 cells have low basal levels of IDO1 in lung cancer cell lines." (PMID 28903363, 2017). "We assessed whether lung cancer cells alter the expression of the two dioxygenase, IDO1 and TDO2, in LCAF." (PMID 27050278, 2016). "IDO1 over-expression supports tumor growth and progression of lung cancers, leading to hypothesize that kynurenine, besides its immunosuppressive effects, may directly enhance the tumor development." (PMID 25955018, 2015). "In human lung cancers, Ido-1 was being made by eosinophils that were infiltrating the NSCLC." (PMID 22899945, 2012). "Therefore, we hypothesized that QFM may inhibit IDO1 for improving tryptophan metabolism by down-regulating STAT1 phosphorylation to decrease PD-1 expression in CD8+ T cells in lung cancer." (PMID 38882349, 2024). "Importantly, this first publication utilizing AT-0174, showed efficacy in preclinical models of non–small cell lung cancer, inhibiting chemoresistant tumor growth, compared with single inhibition of IDO1, supporting that TDO2 or dual inhibition is necessary for a robust antitumor response." (PMID 38451784, 2024). "Moreover, IDO1 is a promising anticancer target for different cancer treatments including lung cancer whose function can be regulated by small candidate molecules and the process provides immune blockade opportunities outside the immune checkpoint inhibition and adoptive immune cell transfer." (PMID 35938038, 2022). "Therefore, IDO1 might be a potential response marker of immune checkpoint inhibitors in lung cancer patients with a smoking history." (PMID 36068203, 2022). "However, IDO1 is highly expressed in variety of kinds of tumors including lung cancer." (PMID 35187162, 2022). "Down-regulation of IDO1 could enhance gemcitabine sensitivity of lung cancer cell A549." (PMID 31315643, 2019). "Besides, CCR7, CST7, GPR143, HDAC5, and IDO1 are also related to lung cancer or the MAPK pathway." (PMID 30972101, 2019). "We detected that knockdown of IDO1 could inhibit lung cancer cell migration and invasion." (PMID 28903363, 2017). "Interestingly, when 64 lung cancer samples were stratified according to the lymph node-metastasis status (Postoperative lymph node examination was positive), we found that IDO1 was significantly up-regulated in lung cancer that had lymph node-metastasis (P <0.001)." (PMID 28903363, 2017).
lung carcinoma (continued). "In addition, our functional studies further found that IDO1 played a major role in lung cancer metastasis, and overexpression of IDO1 could promote migration and invasion in vitro and metastasis in vivo." (PMID 28903363, 2017). "In lung cancer, IL‐6 activates STAT3 to induce IDO1, which in turn produces Kyn and KYNA to activate AhR and induce IL‐6 expression." (PMID 40103267, 2025). "Preclinical studies from our group and others have demonstrated that dual inhibition of IDO1 and TDO2, especially when combined with anti-PD1 therapy, can significantly improve survival in mouse models of lung cancer." (PMID 39911818, 2024). "In this study, 6 hub genes,NKX2-1,CD8A,SFTA3,IL2RB,IDO1, andCXCL9, which are all M1 macrophage coexpressed genes, were utilized to build the immunotherapy response model.NKX2-1 can regulate lung cancer growth by targeting the MAPK pathway." (PMID 38379417, 2024). "In the immune microenvironment of lung cancer, IFN-γ mediates the phosphorylation of STAT1 and promotes the expression of IDO1 in LC cells." (PMID 38882349, 2024). "Next, we detected the expression of AhR pathway genes (IDO1, AhR, CYP1A1, and CYP1B1) in SARS-CoV-2–infected and mock-infected human lung cancer cells (H1299 and Calu-3)." (PMID 37256962, 2023). "IDO1 has been identified as a key marker in the IFN-γ signature and gene signature predictive of response to ICIs in lung cancer." (PMID 37292921, 2023). "In this study, we aimed to investigate the correlation between IDO1 activity and radiation-induced lung toxicity (RILT) in stage III nonsmall cell lung cancer (NSCLC) patients who were treated with chemoradiotherapy (CRT)." (PMID 36824664, 2023). "The levels of IDO1, IDO2, and TDO proteins were evidently declined compared with those of lung carcinoma model rats (P < 0.05)." (PMID 34399782, 2021). "In vivo and in vitro experiments showed that the simultaneous overexpression of IDO1 and GBP1 can promote the migration and invasion of lung cancer cells." (PMID 33552086, 2020). "In order to verify the role of IDO1 and GBP1 in lung cancer species, western blot was performed to detect the expression levels of IDO1 and GBP1 in 6 lung cancer cell lines." (PMID 33552086, 2020). "In addition, we found that ODNs with six or more consecutive guanosines (ODNs with poly‐G sequences) may competitively inhibit the IFN‐γ receptor and abolish the effect of IFN‐γ, thereby suppressing apoptosis and indoleamine 2,3‐dioxygenase 1 expression in human lung cancer cells." (PMID 32067413, 2020). "This indicated that inhibiting the extracellular secretion of IDO1 by blocking the interaction of IDO1 and GBP1 can also inhibit the malignant progression of lung cancer cells." (PMID 33552086, 2020). "In vitro study showed that the high expression levels of IDO1 and GBP1 in lung cancer cells promoted cell invasion and migration." (PMID 33552086, 2020). "This study showed that IDO1 can bind to GBP1 and increase the extracellular secretion of IDO1 with the assistance of GBP1, thereby promoting the malignant proliferation and metastasis of lung cancer." (PMID 33552086, 2020). "Then the effects of IDO1 and GBP1 on the invasion, migration and colony formation ability of lung cancer cells were tested by transwell, wound healing and colony formation assay." (PMID 33552086, 2020). "Conversely, we transfected si-IDO1 into NCI-H1299 cells, which have relatively high endogenous IDO1 expression among lung cancer cell lines." (PMID 28903363, 2017).
lung carcinoma (continued). "Moreover, IDO1 downregulates the natural killer group 2D ligand via ADAM10, impairing natural killer cell function and facilitating non‐small cell lung cancer progression." (PMID 41332472, 2025). "It has to be noted that the Kyn/Trp ratio is not fully reflecting IDO1 activity in vivo, but there is evidence for the prognostic value of the Kyn/Trp ratio in glioblastoma, nasopharyngeal carcinoma and non‐small cell lung cancer patients." (PMID 39308420, 2025). "In our recent preclinical studies, dual inhibition of IDO1 and TDO2 with the novel agent AT-0174 effectively reduced KYN levels, increased tumor infiltration with natural killer cells, and reduced regulatory T cells in cisplatin-resistant lung cancer models." (PMID 39911818, 2024). "RNAseq data for the 7 lung cancer cell lines (Minna lab, dbGaP Study Accession phs001823.v1.p1), we determined that TDO2 mRNA was elevated in A549, H1792, H2347, and H2228 cells, while IDO1 and IDO2 were low in most cell lines." (PMID 37985999, 2023). "In tail vein mice, knocking down IDO1 and GBP1 can inhibit the metastasis of lung cancer cells." (PMID 33552086, 2020). "In addition, astragaloside IV can block the combination of IDO1 and GBP1 to inhibit the progression of lung cancer." (PMID 33552086, 2020). "IFN-γ upregulated IDO1 in all four colon cancer cell lines and two lung cancer cell lines, as well as in noncancerous colon epithelial CCD-841 cells, but not in immortalized lung epithelial BEAS-2B cells." (PMID 29685162, 2018). "Firstly, we determined the IDO1 expression levels in 64 pairs of primary lung cancer and their corresponding non-tumorous tissues by qRT-PCR." (PMID 28903363, 2017). "Whereas, we discovered that IDO1 expression was up-regulated by more than 3.2-fold in lung cancer compared with non-tumorous tissues." (PMID 28903363, 2017). "As results, we reported that IDO1 expression increased by more than 3.2-fold in lung cancer compared with their corresponding non-tumor tissues, and the up-regulation of IDO1 is significantly correlated to TNM stage and lymph node-metastasis." (PMID 28903363, 2017). "IDO-1 expression with IFN-γ stimulation has also been observed in colorectal and lung cancers." (PMID 25415278, 2014). "The relationship between IDO1 and angiogenesis marker expression in cancer has not been analyzed by bioinformatics analysis, even though the positive effect of IDO1 expression on angiogenesis in ovarian tumor and lung cancer had been reported." (PMID 39065567, 2024). "Cell counts revealed that epacadostat at 20 nM concentration for 4 days did not decrease viability of these cells, indicating that IDO1 activity may not directly induce lung cancer cell growth in monolayer cultures." (PMID 37985999, 2023). "The different correlation profiles of IRF1, eIF2α, ATF4, and PDL1 protein expressions in the normal and tumor tissues of lung cancer, especially adenocarcinoma, may be helpful in selecting conditions for combining ICI and inhibitors against IDO1 or modulators of ER stress." (PMID 30305853, 2018). "Furthermore, we isolated F4/80+ TAMs from PBS- or HCQ-treated mice with orthotopic lung cancer, and we found that the M1-like molecules (Nos2, Ifng, IL12b,and IL1b) were up-regulated and the M2-like molecules (Arg1, Tgfb1, IL10, and Ido1) were down-regulated with HCQ treatment." (PMID 30373678, 2018). "Whereas, evident proof for IDO1's influence on invasion or metastasis in lung cancer is lacking." (PMID 28903363, 2017).